TNF (tumor necrosis factor)
Diseases named in the same sentence as TNF in open-access papers (continued):
Sharing a sentence is not in itself a finding about the gene and the disease.
Obesity (continued). "Given that placental Ras expression and activity was increased with maternal obesity, we stimulated primary human trophoblast cells with bacterial endotoxin LPS or with proinflammatory cytokines IL-1β or TNF-α in order to mimic the inflammatory environment that is associated with obesity." (PMID 30402038, 2018). "Obesity, particularly visceral, is strongly associated with dysregulated expression of inflammatory cytokines such as tumor necrosis factor-alpha (TNF-α), interleukin-1 beta (IL-1β), and IL-6, as well as adiponectin and leptin, contributing to metabolic derangement and insulin resistance." (PMID 29910818, 2018). "Increased TNF-α and IL-6 production has been observed in adipose tissue taken from obese rodent or human subjects, and they have also been implicated as causative factors in obesity-associated insulin resistance and the pathogenesis of T2DM." (PMID 30914847, 2018). "In particular, TNF-α secreted from adipose tissue and from the infiltrated macrophages in adipose tissue may play an important role in developing obesity-associated IR." (PMID 29614722, 2018). "In the state of obesity, excessive energy triggers NF-κB signaling pathways and may disrupt insulin signaling pathway via induction of TNF-α secretion by WAT, which in turn causes IR37." (PMID 29487289, 2018). "Under nutrient overload, as seen in obesity, peroxisomal numbers and/or activity can be impaired as a result of micronutrient deficiencies and/or excessive inflammatory cytokine (e.g., TNF-α) accumulation resulting from elevated oxidative stress and the accumulation of metabolic by-products." (PMID 29527173, 2018). "The purpose of this study was to evaluate the effect of weight loss induced by surgery for obesity and weight-related diseases on pro-inflammatory cytokine (TNF-α) and anti-inflammatory adipokine (adiponectin) levels, and on an adipose-derived hormone (leptin) in severely obese subjects." (PMID 29497960, 2018). "However, there are a few studies regarding the effects of this TNF-α gene polymorphism on obesity and prediabetic individuals." (PMID 30134857, 2018). "Collectively, obesity-associated increases of systemic TNFα and IL-6 might impact HCC initiation and progression via redundant and opposing functions of downstream signaling molecules." (PMID 30591653, 2018). "Disturbances in the metabolism of TNF-α have been implicated in various metabolic disorders, such as obesity and insulin resistance, indicating that changes in the metabolism of TNF-α may affect the onset of T2DM, as well as the progression of the disease." (PMID 30914847, 2018). "TNF-α is always associated with obesity and other markers of inflammation." (PMID 28241808, 2017). "Obesity may cause chronic, low-grade systemic inflammation through increased levels of TNF-α, IL-6, leptin, free fatty acids, and TLR4 and decreased adiponectin levels." (PMID 29049401, 2017). "More generally, it is possible to assume that the association between obesity and periodontal diseases is probably based on the effect of pro-inflammatory cytokines (i.e.Tumor necrosis factor-α-TNF-α-;granulocyte/ macrophage colony-stimulating factor-GM-CSF-,etc.) released by adipose tissue." (PMID 29290840, 2017). "Interestingly, arginase is upregulated by hypoxia, TNF-α, and superoxide anion (derived from uncoupled eNOS), all occurring in obesity and can act together increasing the susceptibility to diabetes in obese individuals." (PMID 28607631, 2017). "Apart from that, obesity caused by high-fat would occasionally cause chronic low-grade inflammation characterized by macrophage infiltration in the adipose tissue where changes in relevant inflammatory factors, such as TNF-α and IL-1, were also detected." (PMID 28077800, 2017). "Knockout of TNF-alpha decreased obesity-caused insulin resistance." (PMID 29209160, 2017).
Obesity (continued). "Growing evidence reveals that the accumulation of adipose tissue leads to the development of systemic inflammation (e.g. increases in circulating levels of tumor necrosis factor-α and interleukin-6), which accounts for the obesity-associated vasculopathy and cardiovascular risks." (PMID 28738856, 2017). "However, in atopic asthmatic children and adolescents, obesity has been associated with increased serum leptin and tumor necrosis factor alpha (TNF-α) levels that enhance eosinophil chemotaxis and adhesion." (PMID 28696379, 2017). "Studies have shown that IL-17 could stimulate the production of TNF-α, the first cytokine being associated with obesity and insulin resistance." (PMID 28251163, 2017). "Additionally, similar to obesity is the upregulation of factors like TNFα and IL-6 that are implicated in the development of insulin resistance and glucose intolerance." (PMID 28212318, 2017). "Besides leptin, other pro-inflammatory cytokines - Interleukin-6 (IL-6) and tumor necrosis factor (TNF) are linked strongly to obesity and have been found to have a role in development of CC." (PMID 28819564, 2017). "It is known that TNFα is closely associated with obesity-induced chronic inflammation." (PMID 28248545, 2017). "However, we were unable to detect statistically significant differences in inflammatory cytokines that are traditionally associated with obesity including TNF-α and IL-6, two standard markers of an inflammatory response." (PMID 28873415, 2017). "We initially speculated that the inverse relationship with C-peptide and D5D EAEs was likely due to underlying obesity-associated inflammation, since inflammation (i.e. TNF-α) alters insulin downstream signaling." (PMID 27023786, 2016). "Obesity presents a chronic, low grade vascular inflammation, caused by macrophage infiltration, increased level of proinflammatory adipokines (leptin, resistin) and cytokines levels (IL-6, TNF alpha), and reduced levels of protective adiponectin." (PMID 27092288, 2016). "In addition, TNF-α or TNF-α receptors deficient mice are protected against obesity-induced insulin resistance and hyperglycemia." (PMID 27562094, 2016). "TNF-α modulates lipid metabolism and is associated with obesity." (PMID 27517955, 2016). "Besides obesity, dysregulation of TNF production has been implicated in a variety of human diseases, including Alzheimer’s disease, cancer, rheumatoid arthritis, and IBD." (PMID 27148273, 2016). "Specifically, some of the most known candidate genes and genetic loci for asthma and allergy have already been linked to the pathogenesis of obesity such as the tumor necrosis factor alpha (TNF-a) gene, the protein kinase C alpha (PRKCA) gene and β2‐adrenergic receptor (ADRB2)." (PMID 27411394, 2016). "However, it is now well accepted that WAT is a key player in the development of a chronic low-grade inflammation associated with adiposity and consequently obesity with elevated production of pro-inflammatory cytokines, such as TNFα, IL-6, and IL-1." (PMID 27012931, 2016). "Secondly, increased concentration of the pro-inflammatory cytokines such as TNF-α and IL-6 associated with obesity and diabetes might impair insulin action by suppressing insulin signal transduction." (PMID 27581604, 2016). "Also, several hormones associated with insulin resistance and obesity, such as insulin, catecholamines, TNF, and other proinflammatory cytokines, downregulate the expression of adiponectin in adipocytes, resulting in decreased adiponectin serum levels." (PMID 25918733, 2015). "Obesity was reported to be linked with a subclinical inflammatory state with higher concentration of proinflammatory mediators such as interleukin (IL)-1β, IL-6, and tumor necrosis factor (TNF)-α in circulation." (PMID 25722971, 2015). "Moreover, increased leptin, hsCRP and TNFα concentrations were also risk factors for obesity (p < 0.05)." (PMID 25897330, 2015).
Obesity (continued). "Our study suggests that targeting obesity-associated asthma may be required for anti-TNF-α treatment in asthma." (PMID 25658739, 2015). "It is the M1 macrophage phenotype which is associated with obesity and adipose tissue inflammation, is responsible for TNF-α and IL-6 production, and may predominate during the early stages of tumorigenesis." (PMID 26132316, 2015). "Hyperglucosemia and insulinemia, indicating disturbed glucose regulation, and inflammation as seen by increased TNFα levels, were found associated with the obesity, implicating these as possible mechanisms involved in the association between obesity and intestinal tumorigenesis." (PMID 26347815, 2015). "Earlier data positively linked BMI to TNF-α serum levels, but methodological discrepancies, such as the criteria used to assess CP and obesity and the laboratorial tests applied to quantify the serum levels may reflect the differences between samples." (PMID 26330934, 2015). "Indeed, both obesity and aging are associated with pro-inflammatory states where high levels of C-reactive protein, IL-6 and TNF were found in the blood." (PMID 26604973, 2015). "Indeed, obesity is described as being a state of low-grade chronic inflammation in which increased IL-6, IL-8, and TNF-α levels have been described as obesity-induced risk factor of CVD." (PMID 25918477, 2015). "It has been speculated that its reduced levels in obesity may be caused by the enhanced production of proinflammatory cytokines, in particular, by the tumor necrosis factor α (TNFα)." (PMID 26236690, 2015). "We quantified mRNA abundance of AhR, CYP1A1 (as a marker of AhR activation) and TNF-α (as a marker of inflammation) in adipose tissue of obese mice experiencing weight loss (mice were exposed to PCB-77 during the weight-gain phase of diet-induced obesity)." (PMID 25734695, 2015). "Low-grade inflammation in adipose tissues associated with obesity seems involved in the mechanism of the increased plasma AM level in obese subjects, because the AM production is up-regulated by inflammatory cytokines such as TNFα or IL1β." (PMID 25573159, 2015). "Moreover, obesity is associated with increased production of proinflammatory adipokines, including monocyte chemoattractant protein-1, interleukin-6 (IL-6), and tumor necrosis factor-α (TNF-α)." (PMID 25785277, 2015). "Thus, finding natural and safe dietary supplements able to modulate adipocytes function in general, and TNF-α signaling pathway in particular, would be of value to prevent obesity associated diseases." (PMID 25789857, 2015). "In addition to the storage of lipids in the adipose tissue, adipocytokines like adiponectin, leptin, TNF, IL-6, resistin play an important role in tissue physiology and have been shown to be linked to obesity, insulin resistance and β-cell dysfunction." (PMID 28702225, 2015). "IL-6 and TNF-α have been observed to have a positive association with obesity in urban dwellers." (PMID 26391589, 2015). "As inflammatory cytokines, including tumor necrosis factor alpha (TNFα) and interleukin 1 beta (IL1β), were reported to increase AM production, low-grade inflammation in fat tissues associated with obesity is assumed to be involved in the increased expression of AM." (PMID 25573159, 2015). "Obesity, and in particular visceral obesity, is associated with many metabolic effects including a chronic release of pro-inflammatory cytokines such as tumor necrosis factor (TNF-α)." (PMID 24763115, 2014). "Moreover, loss of TNF-α in obesity resulted in improved insulin sensitivity and glucose homeostasis." (PMID 25157251, 2014). "Elevated levels of the proinflammatory cytokine TNF-α are associated with obesity." (PMID 24903457, 2014). "Inhibition of ZAG expression and release by TNFα may increase the susceptibility to lipid accumulation in adipose tissue and liver in obesity state." (PMID 24665369, 2014).
Obesity (continued). "The accumulation of adipose tissue macrophages (ATMs) is a hallmark of obesity-induced adipose inflammation, and inflammatory mediators (TNF-α, IL-6, and MCP-1) released from the ATMs play a crucial role in promoting obesity-related systemic inflammatory conditions." (PMID 25477711, 2014). "Obesity is associated with migration of bone marrow-derived macrophages into the visceral adipose tissue where they acquire an M1 (classical activation) phenotype and secrete proinflammatory cytokines such as IL-1, IL-6, and TNF-α." (PMID 24823865, 2014). "Interestingly, various hormones associated with insulin resistance and obesity including catecholamines, insulin, glucocorticoids, TNFα and IL-6 down-regulate adiponectin expression and secretion in fat cells in vitro." (PMID 24968098, 2014). "Adipocytokines such as TNFα, IL-6, adiponectin, leptin, visfatin, and resistin are cytokines secreted primarily by visceral adipose tissue and are thought to be involved in the positive correlation between obesity and the increased risk of gastric cancer." (PMID 24929539, 2014). "Furthermore, adiposity, especially in the context of obesity and metabolic syndrome, is associated with high levels of IL-6 and TNF-α." (PMID 25338520, 2014). "Serum TNF-α levels are increased in obesity and decreased with weight loss." (PMID 25548896, 2014). "Obesity-related increase in IL-6 may also contribute to the obesity, and it has been described that increased IL-6 production was linked with high TNFα expression." (PMID 24522555, 2014). "Thirdly, due to the production of inflammatory cytokines such as interleukin-6 tumor necrosis factor-alpha and platelet activating factor from adipose tissues, obesity is considered as one of the major risk factor for cardiovascular events such as in-stent re-stenosis." (PMID 24580749, 2014). "The chronic inflammatory response caused by obesity and enhanced production of IL-6 and TNFα may also increase the risk of many cancers." (PMID 25258478, 2014). "It has been hypothesized that dysregulated production of adipocytokines (PAI-1, leptin, resistin, visfatin, adiponectin) and cytokines (TNF-α and IL-6) from accumulated fat participates in the pathogenesis of obesity-associated MS." (PMID 25548896, 2014). "hsCRP is more sensitive marker associated with obesity than IL-6 and TNF-α." (PMID 24507240, 2014). "Chronic activatated JAK-STAT3 pathway has been summarized to contribute to obesity and peripheral insulin resistance as well as leptin resistance.On the other hand, TNF-α is one of the best described causative factors in obesity-associated insulin resistance and the pathogenesis of T2D." (PMID 24465695, 2014). "The infiltrating macrophages in obesity have also been incriminated in development of cancer cachexia as it causes an increase in the release of other inflammatory cytokines such as IL-6 and IL-1b in addition to TNF-α and prostaglandin E2." (PMID 24758278, 2014). "Obesity-associated insulin resistance (IR) is consistently associated with elevated levels of proinflammatory cytokines such as TNFα, IL-6, and IL-1β, and neutralization of TNFα improves insulin sensitivity in obese rodents." (PMID 23577240, 2013). "In recent years, it has been demonstrated that obesity is associated with low-grade inflammatory process characterized by the increase in circulating levels of pro-inflammatory cytokines such as IL-6, TNF-alpha, and acute-phase proteins (CRP and haptoglobin) in healthy obese subjects." (PMID 23690772, 2013). "Circulating TNF-α is increased in obesity and decreased with weight loss." (PMID 23690772, 2013). "Additionally, obesity reduces the response rate to anti-TNF α therapy in RA but increases the risk of developing RA." (PMID 23922673, 2013). "In fact, because it has been shown that adipocytes express and secrete TNF-alpha, adipose body mass may be an important mediator to explain the relation between obesity and inflammation." (PMID 23690772, 2013).
Obesity (continued). "The macrophage accumulation in adipose tissue under an inflammatory state is a hallmark of obesity-induced insulin resistance, and the macrophages are responsible for almost all adipose tissue expression of TNF-α and IL-6, the markers of adipose macrophage polarization and inflammation." (PMID 23533500, 2013). "It is known that obesity is associated with elevated infiltration of macrophages into adipose tissue, which are principally responsible for the increased production of adipose tissue-derived TNF-α." (PMID 24098322, 2013). "TNFα is a major pro-inflammatory adipokine that is upregulated in fat tissue of obese animals and humans, and causes adipose tissue inflammation and insulin resistance in obesity." (PMID 24358263, 2013). "TNFα is often found in adipose tissue as well as in human fat, and the levels of its mRNA have been closely linked to the prevalence of hyperinsulinemia and obesity." (PMID 24324517, 2013). "Diet-induced obesity-associated inflammation is characterized by an increased abundance of M1 macrophages in the adipose tissue, which are postulated to be major sources of several molecular mediators, such as TNF, IL-6, and C-reactive protein." (PMID 23922979, 2013). "Importantly, increased TNF-α is associated with insulin resistance in obesity, aging, sepsis, and after muscle damage." (PMID 23691290, 2013). "Additionally, obesity is associated with low-grade inflammation and slightly elevated levels of cytokines such as IL-6, IL-8, and TNF-α in body fluids and tissues." (PMID 23936654, 2013). "Obesity is associated with a state of chronic or low grade systemic inflammation which increases production of obesity-related inflammatory cytokines, such as IL-1β, IL-6, TNFα, leptin and decrease anti-inflammatory cytokine levels, such as adiponectin." (PMID 24143244, 2013). "TNF-α has been implicated in the pathology underlying obesity and T2D." (PMID 23984304, 2013). "This drug not only reduced the inflammatory responses in adipocytes (e.g., it caused a downregulation of inflammatory markers such as tumor necrosis factor-α and interleukin-6) but also in vivo Bay-X-1005 prevented hepatic steatosis created in a mouse model of dietary obesity." (PMID 23762565, 2013). "Furthermore, cytokines associated with obesity and insulin resistance such as tumor necrosis factor α (TNFα) can drive lipolysis and fatty acid release from adipose." (PMID 22701716, 2012). "Migraine patients may have multiple metabolic abnormalities associated with obesity, including cerebrospinal fluid (CSF) neuropeptide Y elevation, CSF tumor necrosis factor alpha (TNF) elevation, and systemic adiponectin depression." (PMID 23181051, 2012). "For example, central administration of TNF-α at low doses faithfully replicated the effects of central metabolic inflammation in enhancing eating, decreasing energy expenditure, and causing obesity-related hypertension." (PMID 22328600, 2012). "Furthermore, mast cells containing immunoreactive tumor necrosis factor-α (TNF-α), a proinflammatory cytokine involved in obesity-linked insulin resistance, were identified by immunostaining." (PMID 22313574, 2012). "Following treatment with the obesity-associated inflammatory mediator TNFα, unknown adipocyte mechanisms are altered resulting in an increased ratio of active to total chemerin production." (PMID 23227233, 2012). "TNF-α was one of the first cytokines identified and is involved in the systemic inflammatory response; additionally, it has also has been linked with the development of insulin resistance, obesity, and diabetes." (PMID 21686173, 2011). "Obesity is associated with "low-grade inflammation", a term that is used to reflect increments in the systemic concentration of tumour necrosis factor-alpha (TNF-α), interleukin (IL)-1β, IL-6, IL-1ra, and C-reactive protein (CRP)." (PMID 21599899, 2011). "Furthermore, in humans, enhanced TNF-α expression in adipose tissue is associated with insulin resistance and obesity." (PMID 19781706, 2010).